CCNB1 (cyclin B1)
Diseases named in the same sentence as CCNB1 in open-access papers (continued):
Sharing a sentence is not in itself a finding about the gene and the disease.
cancer (continued). "Additionally, the downregulation of other proteins that have a role in endometrial and other cancers, including SYK, FOXO3A, and cyclin B1, offers insights into the worst survival of the low-muscle/all adiposities group compared to the others." (PMID 39766121, 2024). "We observed that CCNB1 expression significantly correlates with the infiltration levels of CD8+ T-cells, CD4+ T-cells, macrophages, neutrophils, myeloid dendritic cells, and B cells in many cancer types." (PMID 38581717, 2024). "Altogether, RRM2, CCNB1, HMMR, and EZH2 seemed to be key genes in cancer development." (PMID 39118438, 2024). "CCNB1 has also been indicated to be an oncogenic factor in the proliferation of HCC cells, showing a significant impact on the patient’s survival time and thus has been targeted for cancer treatments." (PMID 37438763, 2023). "The results indicated that CCNA2, CCNB1, CDK1 and CDKN2A were expressed in cancer epithelial cells." (PMID 37265472, 2023). "CDK1, CCNB1 and CDK2 are the key oncogenes that promote cell cycle progression in cancer cells." (PMID 35359459, 2022). "Up to this point, it is also interesting to note that most of the GO and KEGG terms based on the DEGs like CCNB1, PLK1 and CDC20 are closely related to anti-cancer patterns, which may point to the anti-cancer potential of our MOL extract preparation." (PMID 36197921, 2022). "Considering a reduction of cyclin B1 and CDK1 by apigenin has been reported in other cancer cell lines, it is possible that the impeding effect imposed on G2-M transition by apigenin is a general mode of action in a broad range of cancer cells." (PMID 35670862, 2022). "The cancer genes are composed of genes that code for HER2 (HER2 and GRB7), oestrogen genes (ER, PGR, BCL2, and SCUBE2), proliferation genes (MKI67, STK15, BIRC5, CCNB1, and MYBL2), and invasion genes (MMP11 and CTSL2) as well as GSTM1, CD68, and BAG1." (PMID 36042999, 2022). "Similarly to CCNA2, overexpression of CCNB1 and CDK1 has been detected in several human cancers, including PDAC." (PMID 36359879, 2022). "The aim of this study was to identify molecular gene signatures, responsible for cancer initiation, progression, resistances and to treatment, metastasis, and also evaluate the potency of our novel compounds SJ10 as potential target for CCNB1/CDC42/MAPK7/CD44 oncogenic signatures." (PMID 35008426, 2022). "It should be noted that infinite proliferation potential is a common feature for most types of cancer, so CDK1, CCNB1, and KIAA0101 were broadly expressed and upregulated in a variety of cancers, making them unsuitable for use as CCA biomarkers but suitable for therapeutical targets." (PMID 36224755, 2022). "In pan-cancer levels, STIL showed consistent expression alteration with CDK1 and CCNB1." (PMID 35155425, 2022). "An in vitro analysis on A431 human carcinoma cells revealed that HSP (10–500 μM) upregulated ROS production, JNK1/2, p38, Bax, p21 expression and suppressed the expression of ERK1/2, cyclin B1, D1, D3, E1, thereby leading to apoptosis and reduced cell viability." (PMID 35128104, 2022). "A recent study that used protein microarrays to screen for the presence of 30 aAbs in nasopharyngeal cancer patients also showed that NY-ESO-1 (along with cyclin B1, survivin, and IMP3) could serve as a biomarker for the detection of this type of cancer." (PMID 34360795, 2021). "CCNB1 and CCNB2 were overexpressed in multiple human cancers." (PMID 34497666, 2021). "Meanwhile, CCNB1, CCNB2, and CDK1 are highly expressed in almost all cancer types, which may play an important role in cancer." (PMID 34337056, 2021).
cancer (continued). "When over-expressed, PER1 was shown to set off apoptosis associated with DNA damage and altered expression of critical cell cycle controllers, such as WEE-1, Cyclin B1, and CDC2 in various human breast (MDAMB-231), colon (SW48), lung (NCI-H460), and endometrial (Ishikawa) cancer cell lines." (PMID 34440260, 2021). "In the end, the molecular function of Cdc20 in pan-cancer analysis indicated that BUB1, CCNA2, CCNB1, CDK1, MAD2L1, and PLK1 might play a critical role in its oncogenic function." (PMID 34527589, 2021). "Furthermore, in HT-29 cells, platelets-cancer cells’ direct interaction induced COX-2-dependent PGE2 production leading to the regulation of p21 and cyclin B1 gene expression and the EMT promotion." (PMID 34439397, 2021). "In addition, in human malignant tumors, inhibition of CDC20 in growing cells leads to G2 arrest with a consequent decrease of cyclin B1, securin, and cyclin A." (PMID 34513754, 2021). "Since UCHL1 affects the protein stability of target proteins in other cancer types by deubiquitination, we sought to determine whether UCHL1 directly affected the protein stability of cyclin B1." (PMID 31906456, 2020). "Currently, the exact role of cell cycle regulatory protein, cyclin B1 in cancer cell growth development, progression and metastasis is not completely understood." (PMID 31126091, 2019). "Among them, both of CCNB1 and CCND1 are overexpressed in many cancers." (PMID 31592235, 2019). "The gene expression levels of cyclin B1 (CCNB1), cyclin B2 (CCNB2), Aurora A (AURKA), Aurora B (AURKB), and PLK-1 (PLK1) were increased from stages 1 to 4; however, the genes for D-type cyclins were expressed in a stable manner across the cancer stages." (PMID 30235818, 2018). "As we know, cyclin B1 is related to cell cycle and cell phase transition (G2/M) in cell proliferation, while Ets-1 and Snail are related to cell growth, proliferation, epithelial-mesenchymal transition (EMT), and cancer cell migration and invasion." (PMID 28881808, 2017). "The FOXM1 transcription factor is a proto-oncogene involved in cell cycle progression, cell proliferation, tumorigenesis and cancer progression, and many of its target genes (> 20) were downregulated in paclitaxel-residual MDA-MB-231 cells including AURKB, CCNB1, PLK1, PLK2, and the kinesin KIF20A." (PMID 28187446, 2017). "In all three cancer cell lines, Western blot analysis showed a decrease of p-H3, cyclin B1, and AURKB, 72 hr after LOX knockdown, but not with BAPN treatment." (PMID 27296552, 2016). "Having established the roles of ERLIN2 in stabilizing microtubules and Cyclin B1 complex, we asked whether downregulation of ERLIN2 could affect cancer cell proliferation and malignancy." (PMID 27462423, 2015). "Our study demonstrates that USP22 is a CCNB1 deubiquitinase, suggesting that targeting USP22 might be an effective approach to treat cancers with elevated CCNB1 expression." (PMID 27030811, 2015). "The effects of 2-ME on Cdk1 expression and activity and on cyclin B1 expression have been widely investigated in numerous cancer cell lines, but not in HeLa cells." (PMID 26228523, 2015).
cancer (continued). "Western blotting analysis showed that p21 and Rb were significantly increased in the cancer cells stably expressing Lin28 compared to the mock controls, whereas Cyclin B1 and AKT expression did not change." (PMID 22808086, 2012). "By analyzing the clinical significance and prognosis of G2/M related genes (PLK1, CDK1, CCNB1, and CCNB2) in various cancer tissues, we found that they were up-regulated in most cancer types, and their down-regulation showed better overall survival rates in cancer patients." (PMID 37007025, 2023). "Additional experiments indicated that IND-2 could produce its anti-cancer efficacy by inducing oxidative stress, decreasing the mitochondrial membrane potential and inhibiting metastasis by altering the levels of Wnt 5a/b, DVL3, E-cadherin and cyclin B1." (PMID 36431014, 2022). "Likewise, icodextrin did not significantly alter the expression of cyclin B1 or cyclin D1 in a time-dependent manner in either cancer cell line." (PMID 35334562, 2022). "Since CCNB1 overexpression promotes tumorigenesis, and the overexpression of miRs miR-744 and miR-1186 phenocopies CCNB1 overexpression, this work indicates that TGA may be a process through which miRs can contribute to cancer development." (PMID 35327968, 2022). "Moreover, the pan-cancer analysis of the molecular function of Cdc20 indicated that BUB1, CCNA2, CCNB1, CDK1, MAD2L1, and PLK1 might play a critical role in interaction with Cdc20." (PMID 34527589, 2021). "Knock-down and overexpression studies in cancer cell lines suggest that Usp22 may promote cancer through the positive regulation of well-known oncogenes including BMI1, c-MYC, SIRT1, cyclin B1, and KDM1A, mainly through the regulation of cell cycle progression." (PMID 34503086, 2021). "We found that four genes are highly expressed in HCC, among which four genes, CCNB1, CNB2, CDK1, and CYP3A4, are highly expressed in tumors, while CCNB1, CCNB2, and CDK1 are highly expressed in almost all cancer types, which may be involved in the important tumorigenesis or progression." (PMID 34337056, 2021). "Under normal growth conditions, binding of the cyclin B1 to CDK1 is necessary for CDK1 activation and initiation of its phosphorylation at threonine residue 161 (Thr 161), thereby commit the mitochondrial metabolism for adaptive cell cycle progression and resistance of cancer cells." (PMID 34064109, 2021). "Thus, when the p21 level is decreased by TERT in cancer cells, the expression level of CCNB1 can be increased because CCNB1 is no longer inhibited by p21." (PMID 31856825, 2019). "Thus, although CCNB1 and CCNB2 have been previously reported to act as therapeutic target genes in HCC, the clinical significance of CCNB1 and CCNB2 needs to be investigated in cancer-related research." (PMID 31886163, 2019). "Because p21 and cyclin B1 play positive and negative roles, respectively, in G2/M arrest, we examined the expression of these proteins in CQ-treated cancer cells and found that CQ increased the p21 level but decreased that of cyclin B1, compatible with G2/M phase arrest." (PMID 29513749, 2018). "Hence, less CDK1-Cyclin B1 complex could be formed in cancer cells, leading to G2/M arrest and apoptosis, especially in HepG2 cells with less activated CDK1-Cyclin B1 complex." (PMID 27909289, 2016). "Moreover, the functions of CDK1/cyclin B1 in human cancer had not been properly elucidated similar to CDK4/CDK6/cyclin D. Multi-CDK inhibitors that target CDK1 are well-tolerated in cancer patients." (PMID 25914884, 2015).
cancer (continued). "In our results, calycosin affected two check points gene transcription; for example TFDP-1 and SKP2 were markedly downregulated and CDC2 and CCNB1 were upregulated expression and downregulated expression of CDKN2D which may block the G1/S and G2/M transition in cancer cells." (PMID 24455688, 2013). "For this reason we did not include HMMR and CCNB1 in a prognostic cancer model." (PMID 24349376, 2013). "CCNB1 has been shown to be upregulated in HCV-induced HCC, while AEBP1 has been demonstrated to manifest a proinflammatory function by up-regulating NF-kappaB and suggested as a potential therapeutic target for the treatment of various chronic inflammatory diseases and cancer." (PMID 22539975, 2012). "Compared to the noncancerous HDFs, higher levels of cyclin B1 and/or CDK1 were detected in a number of the cancer cell lines." (PMID 32575711, 2020). "The immunohistochemical staining results from HPA database indicated significantly higher positivity for AURKA, CCNB1, CCNF, and EXO1(Not found in HPA database) in cancer tissues than in adjacent normal tissues." (PMID 31087508, 2019). "In cancer models that are genetically independent of CDK2, pharmacological inhibitors suppress cell proliferation by inducing 4N cell cycle arrest and increasing the expressions of phospho-CDK1 (Y15) and cyclin B1." (PMID 39924553, 2025). "However, CCNB1 is a regulatory subunit of CDK1 and is one of the main cyclin family members, it is not convenient to be directly manipulated in anti-cancer therapy." (PMID 27030811, 2015). "Consistent with the cell cycle arrest phenotype, elevated Cyclin B1 protein level was evident by Western blotting in ARK1, AN3CA and RL952 cancer cell lines treated with either LiCl or inhibitor VIII, whereas no induction of Cyclin B1 was seen in EM-TERT cells." (PMID 23941783, 2013).
infection (19 papers, 2012 to 2023). The state of being infected such as from the introduction of a foreign agent such as serum, vaccine, antigenic substance or organism. "To assess the relationship between cyclin B1 and BRCA1 deficiency, we restored cyclin B1 in MCF7 cells by infection with an Ad-cyclin B1, followed by knockdown of the BRCA1 gene." (PMID 30327455, 2018). "As described, MVM uses a very different approach to prevent the activation of the cyclin B1/CDK1 complex: infection inhibits the production of Ccnb1 RNA which leads to the loss of cyclin B1 protein." (PMID 29088070, 2017). "Rather, cyclin B1 and its encoding RNA become substantially depleted during infection." (PMID 29088070, 2017). "Prior studies on the late stages of MVM infection (at 24 hpi and beyond) have identified CRL4Cdt2- mediated p21 degradation and transcriptional repression of Cyclin B1 as key events driving cell cycle arrest at the late stages of infection." (PMID 37253065, 2023). "Western blot analysis indicated that ORFV NA1/11 infection decreased the relative levels of cyclin B1 expression in both A549 and LLC cells relative to that in the controls." (PMID 35959371, 2022). "We found that ORFV NA1/11 infection induced cell cycle arrest in G2/M phase and reduced the relative levels of cyclin B1 expression in both A549 and LLC cells." (PMID 35959371, 2022). "Specifically, we were interested in observing the nuclear localization of cyclin B1 in cells with infection-induced DDR." (PMID 36568985, 2022). "The model of G2/M checkpoint activation was supported by infection-induced nuclear accumulation of cyclin B1 and Cdk1." (PMID 36568985, 2022). "Taken together, capsids escape from the nucleus in late infection when cyclin B1 is accumulated in the nucleus." (PMID 36568985, 2022). "We found a decrease of acetyl-H3 on the CCNB1 promoter at 6 h post-infection, paralleled by an increase of H3K9 trimethylation." (PMID 31492965, 2020). "We demonstrate that activated UHRF1 is recruited to the CCNB1 promoter during infection and induces epigenetic modifications, resulting in the formation of a heterochromatin environment and repression of the CCNB1 promoter activity." (PMID 31492965, 2020). "To establish if UHRF1 is directly involved in cyclin B1 downregulation, we examined the recruitment of UHRF1 to the CCNB1 promoter during infection, by chromatin immunoprecipitation (ChIP) assay." (PMID 31492965, 2020). "A significant increase in cyclin B1 levels was observed at 12 h of infection in UHRF1 knock-down cells, compared with cells transfected with EGFP-siRNA, whereas lower expression is seen for earlier time points." (PMID 31492965, 2020). "Western blot analysis of cyclin B1 in infected MDA-MB-231 cells revealed a strong linear increase of cyclin B1 from 6 to 48 h after infection for all three recombinant viruses." (PMID 28951871, 2017). "Surprisingly, however, during MVM infection, although activity of the cyclin B1/CDK1 complex is lost, the inhibitory phosphorylation of CDK1 at Tyr-15 is absent-typically an indicator associated with activity of the cyclin B1/CDK1 complex." (PMID 29088070, 2017). "Following MVM infection of para-synchronized murine A9 cells, cyclin B1 levels were seen to accumulate at 18 h pi, increasing through the 24 h time point (lanes 4 and 5)." (PMID 24415942, 2014). "This was unexpected because cytoplasmic retention of cyclin B1 is a general mechanism governing cell cycle arrest during infection by various viruses and DNA damage stimuli." (PMID 24415942, 2014). "To further define the disruption in the cell-cycle of GNPCs following infection we assayed the levels of two cyclins, cyclin D1 and cyclin B1, in control and MCMV infected mice." (PMID 23505367, 2013). "Increased Cyclin B1 expression was observed at days 2 (∼6.53-fold) and 8 (∼3.71-fold); it then decreased to the baseline from day 30 to 360 post-infection." (PMID 22253905, 2012).